EGF (epidermal growth factor)
Diseases named in the same sentence as EGF in open-access papers (continued):
Sharing a sentence is not in itself a finding about the gene and the disease.
asthma (45 papers, 2011 to 2025). "Increased EGF receptor expression has long been associated with asthma severity, and is perceived as evidence of an injury and repair response since ligation of the receptor by EGF promotes reepithelialisation and wound healing." (PMID 39592603, 2024). "The potential of such molecules for the treatment of asthma or chronic obstructive pulmonary disease was evidenced with the use of LC-HN/C linked to epidermal growth factor (LC-HN/C-EGF) inhibiting the release of mucin by pulmonary epithelial A549 cells (COPD)." (PMID 33374954, 2020). "Additionally, we observed an increased risk of asthma with elevated concentrations of IL-1RA, and to some extend with EGF, and CCL22." (PMID 31217483, 2019). "The associations of EGF and Periostin with adult-onset asthma were positive but weak." (PMID 31217483, 2019). "One possible mechanism underlying aggravation of asthma by SO2 could be that SO2 derivatives increase the expression levels of EGF, EGFR, ICAM-1, and COX-2 proteins in BEP2D cells." (PMID 30885130, 2019). "Chloroquine and quinine reduced PDGF and epidermal growth factor (EGF)-induced proliferation in normal, asthma, and ASM hyperplasia models." (PMID 39979526, 2025). "A similar approach was used with the coupling of LHN/C to epidermal growth factor (LHN/C-EGF) to inhibit the release of mucin by pulmonary epithelial A549 cells in the treatment of asthma or chronic obstructive pulmonary disease." (PMID 38922155, 2024). "In general, EGF levels are reported as equivalent or lower in individuals with asthma or allergic rhinitis compared to healthy controls." (PMID 39592603, 2024). "It has been reported that the secretion of EGF increases in asthma and EGF can induce the activation of the EGFR-AKT signalling pathway." (PMID 38093206, 2023). "As a member of the epidermal growth factor (EGF)family, amphiregulin (Areg) has been implicated in exerting an important role in regulating tissue repair in acute epithelial injury and asthma." (PMID 36405762, 2022). "VEGF is a potent stimulator of angiogenesis in asthma, and both VEGF and EGF are stimulators of mucins in the respiratory tract, whose concentrations have been reported as positively correlated with asthma disease severity." (PMID 34631615, 2021). "There have been several recent studies demonstrating that pathogenic EGF/EGFR-dependent signaling through EGF and other EGFR ligands, such as amphiregulinin, is increased in asthma." (PMID 33123005, 2020). "EGF and amphiregulin levels increased in sputum during acute childhood asthma compared to those participants with a stable condition." (PMID 33217964, 2020). "To further understand the mechanism(s) by which EGF/EGFR is involved in inducing inflammatory cell influx in the asthma phenotype, we examined the direct and indirect effects of EGF/EGFR signaling on mononuclear and neutrophil chemotaxis in vitro." (PMID 28855674, 2017). "EGF/EGFR has a role to play in the disequilibrium of the bronchial epithelium in asthma and is considered a promising target for pharmacotherapy." (PMID 26057128, 2015). "Other growth factors contributing to airway remodeling in asthma include endothelin-1 (ET-1), epidermal growth factor (EGF), platelet-derived growth factor (PDGF), and vascular endothelial growth factor (VEGF)." (PMID 23853765, 2013). "The fact that only two of the four cytokines measured were upregulated in cultures from healthy subjects suggests a trend for EGF effects to be more pronounced in disease, especially in more severe asthma." (PMID 24039773, 2013). "Many growth factors are also involved in asthma such as EGF, FGF, and TGFs." (PMID 40266878, 2025). "Chronic inflammatory conditions in COPD and asthma could increase fibrogenic growth factors like TGF-β, EGF, and VEGF, all implicated in RBM thickness." (PMID 35997281, 2022).
asthma (continued). "Goblet cell metaplasia and hyperplasia in airway-induced mucin overproduction, in response to many endogenous signaling factors, such as epidermal growth factor (EGF), leukotrienes (LTs), and Th2 cytokines, are widely observed in patients with chronic asthma and severe asthma." (PMID 31073274, 2019). "In asthma, overexpression of EGF/EGFR correlates with disease severity and epithelial injury." (PMID 26057128, 2015). "Not only is EGF widely expressed in airway epithelium, gland and smooth muscle, the growth factor is also involved in the pathological and physiological processes of airway remodeling in asthma." (PMID 25009622, 2014). "Thus, in the present study, outpatients and inpatients with asthma were recruited from the Beijing Shijitan Hospital (Beijing, China) between 2010 and 2011, and the levels of EGF, bFGF, PDGF and VEGF in the serum and induced sputum were detected." (PMID 25009622, 2014). "Cells were either left in culture unstimulated or exposed to EGF, thus mimicking an in vivo situation where the asthmatic epithelium sustains injury and this is followed by repair, features that are central to the pathogenesis of asthma." (PMID 24039773, 2013). "EGF induced the epithelium to produce soluble mediators with neutrophil chemotactic (p<0.001) and pro-survival (p = 0.021) activities which were related to the clinical severity of asthma (trend p = 0.010 and p = 0.009, respectively)." (PMID 24039773, 2013). "EGF plays a critical role in asthma and is a potent stimulator of human airway epithelial cells." (PMID 21695271, 2011). "We have now sought to (i) determine whether this EGF-dependent pro-neutrophil activity is increased in asthma, where EGF and its epithelial receptor are over-expressed, and (ii) elucidate some of the mechanisms underlying this asthmatic epithelial-neutrophil interaction." (PMID 24039773, 2013). "Many ASM cell mitogens are involved in asthma, such as Platelet-Derived Growth Factor (PDGF), TGF-β, Epidermal Growth Factor (EGF), Heparin-Binding EGF, and Vascular Endothelial Growth Factor (VEGF)." (PMID 38891935, 2024). "HDM prestimulation increased the release of IL-18, EGF, TWEAK, and M-CSF and decreased CCL3 in SARS-CoV-2-infected HBECs from patients with asthma in comparison to SARS-CoV-2 infection alone." (PMID 37087523, 2023). "The different growth factors involved in the pathophysiology of asthma include PAF, transforming growth factor (TGF-β), nerve growth factor (NGF), fibroblast growth factor (FGF), epidermal growth factor (EGF), and insulin-like growth factor 1 (IGF-1)." (PMID 37233255, 2023). "Other factors that cause migratory effects in epithelial cells are growth factors TGF-β, EGF and AREG which have been shown to increase in asthma." (PMID 34308764, 2021). "Our study shows that plasma concentrations of IL-1RA, EGF, and CCL22 were elevated in asthma patients compared to the control group." (PMID 31217483, 2019). "Diverse growth factors including PDGF, transforming growth factor, fibroblast growth factor, and epidermal growth factor, are main contributors to ASM remodeling, and their expression levels are directly correlated with asthma severity." (PMID 31695627, 2019). "Airway remodeling of asthma is characterized by subepithelial fibrosis and smooth muscle hyperplasia, which are mediated by cytokines, such as TGF-β, EGF and periostin." (PMID 29257052, 2017). "EGF, bFGF, PDGF and VEGF have important roles in airway inflammation, airway obstruction and AHR during the pathogenesis of asthma." (PMID 25009622, 2014). "First, PDGF‐BB was employed to activate ASMCs; however, other growth factors (e.g., TGF‐β, EGF, and FGF) and inflammatory cytokines (for example, IL‐4, IL‐13, and TNF‐α) may also contribute to ASMC dysfunction in diseases such as asthma." (PMID 40338178, 2025).
asthma (continued). "The higher baseline levels of IP10, TARC, and EGF in the SU2043 group, coupled with the higher prevalence of asthma and atopic dermatitis, suggest that these comorbid conditions and associated biomarkers may reduce the likelihood of achieving SU." (PMID 41200192, 2025). "The EGF/EGFR is a critical signaling pathway in the pathogenesis of asthma, and both EGF and EGFR levels have been shown to be consistently increased in both human asthma and in animal models of asthma." (PMID 33123005, 2020). "Epidermal growth factor (EGF), basic fibroblast growth factor (bFGF), the AA and BB isoforms of platelet-derived growth factor (PDGF) and vascular endothelial growth factor (VEGF) are involved in the pathogenesis of airway inflammation in asthma." (PMID 25009622, 2014). "Eosinophils produce and secrete fibrogenic factors, such as fibroblast growth factor (FGF), heparin binding epidermal growth factor, IL-4, IL-13, IL-17, nerve growth factor, platelet derived growth factor, and transforming growth factor-β (TGF-β), leading to the development of severe asthma." (PMID 36107283, 2023). "For example, LHN/C coupled to epidermal growth factor (LHN/C-EGF) was shown to inhibit the release of mucin from pulmonary epithelial A549 cells, demonstrating the potential of such molecules for the treatment of disorders such as asthma and chronic obstructive pulmonary disease (COPD)." (PMID 29973505, 2018). "Thus the addition of CXCL-1, IFN-γ, IL-5, IL-17A, EGF, eotaxin, IL-lβ, IL-4, IL-12p40, IL-13, and MDC serum concentrations to blood eosinophils and neutrophils adds significant value to the definition of the Difficult-to-Control asthma endotype." (PMID 28686637, 2017). "However, EGF signaling is not appropriately activated by the repairing epithelium in asthma." (PMID 29257052, 2017). "A potential explanation for these observations are that neutrophils from naïve and not from mice with OVA-induced asthma were used and/or that EGF is a not a direct neutrophil chemotactic agent or indeed that other EGFR receptor ligands may be more important in this regard." (PMID 28855674, 2017). "However, a direct link between the observed effects of EGF on endogenous mediator production by the epithelium and neutrophil accumulation has not been established, nor is there evidence that this is a feature of clinical asthma." (PMID 24039773, 2013). "As predicted, treatment with a DP2 antagonist in the absence of a RV-induced exacerbation (akin to ‘stable’ asthma) failed to affect ASM area, collagen deposition, TGF-β1 or EGF expression." (PMID 39592603, 2024).
triple-negative breast carcinoma (45 papers, 2013 to 2025). An invasive breast carcinoma which is negative for expression of estrogen receptor (ER), progesterone receptor (PR), and human epidermal growth factor receptor 2 (HER2). "It was reported that knockdown of SPRY1 can reduce the risk of distant metastasis from triple negative breast cancer via inhibiting EGF/EGFR mediated pathways." (PMID 36035369, 2022). "Some studies have suggested that the expression of epidermal growth factor (EGFR) is relatively high in triple negative breast cancer and it is the main cause growth." (PMID 33934088, 2021). "Homer protein homolog 3 enhances EGF-induced aggressiveness and metastasis via activation of β-catenin in triple negative breast cancer cells." (PMID 39511483, 2024). "Epidermal growth factor (EGF) induces EMT in the triple-negative breast cancer cell (TNBC) line through secretion of IL-6 and IL-8." (PMID 34220337, 2021). "NP-G2-044 treatment decreased the phosphorylation of ERK, PLCγ1, and PI3K downstream of EGF stimulation in EGFR-high triple-negative breast cancer cells." (PMID 32824026, 2020). "Here, we found that a sub-population of ITG β4 is sorted into early endosomes, recycled back to the plasma membrane, and secreted in the form of extracellular vesicles (EVs) upon EGF treatment in triple negative breast cancer (TNBC) cells." (PMID 30545011, 2018). "Taken together, these results indicate that restoration of PTPN5 function inhibits MAPK signaling in response to EGF treatment in tamoxifen sensitive, resistant and triple-negative breast cancer (TNBC) cells." (PMID 29590203, 2018). "Although there are many pathways that regulate BLBC and triple-negative breast cancer, the EGF-NF-κB-FOXC1 signaling axis is presumably specific and essential for BLBC." (PMID 28629477, 2017). "EGF is overexpressed in triple-negative breast cancer and has a synergic role to the induction of angiogenesis by VEGF." (PMID 23981902, 2013). "In addition to increased CXCR4 expression, a stiff ECM also increases basal activation of Akt and ERK as well as signaling through these kinases in response to CXCL12-α and EGF and promotes migration of triple negative breast cancer (TNBC) cells." (PMID 40796929, 2025). "Moreover, EGF-polymeric micelles exerted selective anti-cancer effects against EGFRi-resistant MDA-MB468 refractory triple-negative breast cancer cells after optimization of particle size." (PMID 41140511, 2025). "Moreover, EGF-polymeric micelles exerted cytotoxic effects on MDA-MB468 human triple-negative breast cancer cells, which are generally resistant to EGFR-targeting anti-cancer drugs." (PMID 41140511, 2025). "We explored whether endothelial-derived factors such as EGF and TGFβ (Transforming growth factor β) promote the elongation of triple-negative breast cancer cells." (PMID 38762624, 2024). "It was shown that incubation of BT-20 cells (triple-negative breast cancer cells) with Transforming growth factor-alpha (TGF-α) and A23187, a mobile ion-carrier, caused 13-HODE formation which was dependent on the Epidermal growth factor (EGF) / TGF-α." (PMID 34838055, 2021). "Additionally, SPRY1 was reported to play a selective role in a subset of triple-negative breast cancers to promote the malignant phenotype by enhancing the EGF-mediated mesenchymal phenotype." (PMID 32634115, 2020). "Thus, iEFs were extremely effective in nullifying the pro-migratory effects of EGF(+) on these triple-negative breast cancer (TNBC) cells." (PMID 31428691, 2019). "In addition to c-Src, EGFR is frequently overexpressed in aggressive breast tumors and triple negative breast cancer cell lines, as are a number of downstream components of EGF signaling pathways." (PMID 23762409, 2013). "In triple-negative breast cancer models, CBD significantly inhibits epidermal growth factor (EGF)-induced proliferation, chemotaxis, and activation of ERK and AKT signaling pathway." (PMID 40475776, 2025).
triple-negative breast carcinoma (continued). "To further explore subtype-specific expression patterns, we assessed the expression of CCL18 and EGF across defined molecular subtypes of BRCA, including luminal A, luminal B, HER2-enriched, and triple-negative breast cancer (TNBC)." (PMID 40692603, 2025). "We serum-starved U-2 OS (osteosarcoma) and BT20 (EGFR-amplified triple-negative breast cancer) cells and exposed them to various RTK ligands (EGF, FGF1, PDGF)." (PMID 40667115, 2025). "ERK3 knockdown significantly decreased the levels of both basal and EGF-induced GTP-bound CDC42 and RAC1 in primary (HMEC) and triple-negative breast cancer (MDA-MB231) mammary epithelial cells, respectively." (PMID 37057894, 2023). "In a study on triple-negative breast cancer tissues, researchers found that MDA-MB-231 cells overexpressing oxytocin receptors were more sensitive to Epidermal Growth Factor (EGF) and demonstrated enhanced migration." (PMID 37781188, 2023). "In fact, CBD is known to inhibit EGF-induced activation of EGFR, proliferation, and chemotaxis in triple-negative breast cancer cells, including MDA-MB-231." (PMID 35806150, 2022). "We investigated the role of SHP2 in the responsiveness to EGF by using the EGFR-amplified cell line MDA-MB-468, derived from a patient with triple-negative breast cancer." (PMID 33755016, 2021). "Of note, in triple-negative breast cancer (TNBC) cells, it was shown that epidermal growth factor (EGF) signaling activates the first step of glycolysis, and F-1,6-BP directly binds to epidermal growth factor receptor (EGFR), enhancing its activity." (PMID 34205414, 2021). "The triple-negative breast cancer cell line MDA-MB231 induced HUVEC cell to generate tubes as efficiently as the growth factors VEFG, EGF, and FGF containing EBM-2 medium (46 vs. 51 tubes for MDA-MB231-conditioned medium and EBM-2 medium, respectively)." (PMID 31640747, 2019). "A novel mechanism of triple-negative breast cancer metastasis was recently delineated, and involves the TME factors as peripheral signals, including EGF and insulin-like growth factor-I (IGF-I), at distant indolent tumor sites." (PMID 25857315, 2015). "Mechanistically, PTPN11 enhances the oncogenic activity of β-catenin and activates Src family kinases, as well as regulates focal adhesion kinase (FAK) to promote epidermal growth factor (EGF)-induced lamellipodia persistence and migration of triple-negative breast cancer (TNBC) cells." (PMID 35957898, 2022). "Epidermal growth factor (EGF) signaling upregulates b-1,3-N-acetylglucosaminyltransferase (B3GNT3) expression that promotes N-glycosylation at positions N192, N200, and N219 of PD-L1 in triple-negative breast cancer cells." (PMID 34315872, 2021). "While it has been shown to promote metastasis and macrophage-independent invasion, and act as an effective target for antibody bound nanoparticles for drug delivery in triple negative breast cancer, HBEGF is interesting due to its relationship with the Epidermal Growth Factor (EGF)." (PMID 32620123, 2020). "In SUM159 and SCP2 human tumor cells, as model cells for triple-negative breast cancer, CBD effectively inhibited epidermal growth factor (EGF)-induced tumorigenic properties of these cancer cells by obstructing signaling pathways for EGFR, Akt, ERK, and NF-κB." (PMID 30987191, 2019). "Given the putative role for EGF signalling and hypoxia in mediating tumour progression in vivo, our analysis focussed on the differences between these stimuli in promoting EMT within MDA-MB-468 cells as a model of triple negative breast cancer." (PMID 25975820, 2015).